ENSG00000256966 (novel transcript)
Gene: Protein-coding gene on chromosome 9 (37,512,547 to 37,592,469, reverse strand). Ensembl gene ENSG00000256966.
Genetic constraint (gnomAD): Missense variants: 60 observed, 73.52 expected, observed/expected ratio (o/e) 0.82, 90% interval 0.66 to 1.01. Synonymous variants: 31 observed, 28.83 expected, observed/expected ratio (o/e) 1.08, 90% interval 0.81 to 1.45.